HHLA2 (HHLA2 member of B7 family)
Diseases named in the same sentence as HHLA2 in open-access papers (continued):
Sharing a sentence is not in itself a finding about the gene and the disease.
tumor (71 papers, 2016 to 2026). "Although the precise mechanisms underlying HHLA2’s tumorigenic effects remain to be fully elucidated, growing evidence implicates it in promoting tumor proliferation, invasion, and metastasis." (PMID 40394703, 2025). "There was also a positive association between HHLA2 expression rate and tumor size, and HHLA2 expression correlated with a higher grade and the incidence of nodal and distant spread of PNETs." (PMID 38786018, 2024). "In patients with TNBC, high HHLA2 expression was associated with advanced disease stage at diagnosis and lymph node involvement, but was unrelated to tumor size and age." (PMID 38786018, 2024). "Low HHLA2 expression in tumor cells corresponded to and elevated death risk for patients, but increased HHLA2 expression in CK−CD8−CD68− area cells was also related to a higher risk of death (p = 0.01)." (PMID 38786018, 2024). "The loss of HHLA2 expression on tumor cells during in vitro culture has some parallels with PD-L1 expression." (PMID 37891555, 2023). "The loss of HHLA2 expression on dissociated, in vitro cultured tumor cells indicates a role for a tumor microenvironmental signal that is needed to maintain HHLA2 expression." (PMID 37891555, 2023). "HHLA2 expression in tumor cells is generally associated with more severe disease and poor prognosis, although several studies have reported that high HHLA2 expression is associated with a favorable prognosis." (PMID 37891555, 2023). "Regarding the staging of the tumor, there was a significant association between HHLA2 expression and metastasis." (PMID 34181347, 2021). "The results indicated that high expression of HHLA2 in human tumor tissue was associated with poor OS compared to low expression of HHLA2 (HR = 1.65, 95% CI: 1.12–2.43, P = .011)." (PMID 34397730, 2021). "Higher expression of HHLA2 in ccRCC tissues was positively and significantly associated with larger tumor size and advanced TNM stage." (PMID 31015801, 2019). "The association of HHLA2 with the presence of tumor infiltrating lymphocytes (TILs) and five-year-event-free-survival were examined." (PMID 27531281, 2016). "However, high expression of HHLA2 in tumor cells tended to be associated with better overall survival, although this was not statistically significant (P = 0.08)." (PMID 40255615, 2025). "Additionally, silencing HHLA2 led to the inhibition of M2-type polarization of tumor associated macrophages (TAMs)." (PMID 38762741, 2024). "However, the authors detected HHLA2 expression mainly in tumor-associated macrophages (TAMs) and stromal cells." (PMID 38786018, 2024). "Functional analyses of HHLA2 also confirmed its association with tumor progression." (PMID 36982953, 2023). "Notably, there were large disparities in tumor mutations between the high- and low-expressing HHLA2 groups." (PMID 35371079, 2022). "In addition, the effects of tumor cell‐derived HHLA2 on tumor‐associated macrophage (TAM) polarization were explored." (PMID 34152094, 2021). "In summary, high HHLA2 expression was associated with poor OS in Chinese patients with solid tumors, and might be used as a potential prognostic marker and tumor treatment target." (PMID 34397730, 2021). "However, a statistically significant association was detected between HHLA2 expression and both tumor staging and metastasis." (PMID 34181347, 2021). "In the present study, we performed a comprehensive comparison between HHLA2 and PD-L1 in terms of the expression pattern, clinical relevance and their associations with tumor infiltrating CD3+, CD8+, CD4 + Foxp3+, CD68+, CD163+ and CD20+ immune cells in a ICC cohort after curative resection." (PMID 30885276, 2019). "We also found that the higher expression of HHLA2 was positively and significantly associated with lager tumor size (P = 0.042), and advanced TNM stage (P = 0.041), but we could not find any association with patient’s gender and age." (PMID 31015801, 2019).
tumor (continued). "In the terms of prognostic role, since the over-expression of immune checkpoint stimulator was always associated with a better survival time of tumor patients, these two opposite conclusions about HHLA2 function make the exact prognostic role of HHLA2 still uncertain." (PMID 31379814, 2019). "However, our results revealed that an increased percentage of HHLA2 positive tumor cells was not only associated with high-risk features, but also with worse event-free survival." (PMID 27531281, 2016). "Immune checkpoint analysis showed that, except for HHLA2, which was significantly overexpressed in the low-risk group, the remaining 21 immune checkpoint genes (ICGs) were significantly upregulated in the high-risk population, indicating a more severe state of tumor immunosuppression." (PMID 41322425, 2025). "As studies have reported that tumor-infiltrating lymphocytes may be associated with survival, the association between tumor-infiltrating lymphocytes and HHLA2 expression should be evaluated, and the percentage of tumor-infiltrating lymphocytes and the outcomes should be analyzed." (PMID 36598731, 2023). "Also, this is particularly significant because HHLA2 expression may assist identification of a group of patients who might do poorly in spite of tyrosine kinase inhibitors (TKIs) for EGFR-mutated tumours." (PMID 34181347, 2021). "However, high HHLA2 expression on tumor cells was significantly associated with shorter LFRS." (PMID 35145510, 2021). "In parallel, HHLA2 reshapes the tumor microenvironment through interleukin-10-dependent macrophage M2 polarization, contributing to an immunosuppressive niche." (PMID 42266686, 2026). "Beyond its classical role in T-cell inhibition, HHLA2 appears to integrate tumor-intrinsic oncogenic signaling with immune microenvironment remodeling." (PMID 42266686, 2026). "Recent studies demonstrate that HHLA2 promotes tumor progression by enhancing EGFR/MAPK/ERK signaling, thereby supporting proliferation, invasion, and epithelial-mesenchymal transition." (PMID 42266686, 2026). "Their findings revealed that HHLA2 expression was present in 17.2% of OC cases and significantly associated with better tumor differentiation and increased density of CD8+ tumor-infiltrating lymphocytes." (PMID 40255615, 2025). "The therapeutic efficacy of c-Met inhibition in blocking HHLA2-mediated tumor progression suggests a promising treatment strategy for HHLA2-positive HCC." (PMID 40394703, 2025). "Further validation through immunohistochemical analysis of tumor tissues from our independent cohort of 176 HCC patients in Guangdong, China, confirmed significantly higher HHLA2 protein levels in tumors compared to adjacent non-tumor tissues." (PMID 40394703, 2025). "Conversely, knockdown of HHLA2 via shRNA in Huh7 cells significantly reduced orthotopic tumor growth." (PMID 40394703, 2025). "The research demonstrates that both B7x and HHLA2, at mRNA and protein levels, are significantly overexpressed in tumor tissues compared to adjacent normal tissues." (PMID 40255615, 2025). "This overexpression was associated with lymph node metastasis and advanced TNM stages, suggesting that HHLA2 plays a critical role in tumor progression." (PMID 40255615, 2025). "Co-expression of myc-tagged HHLA2 in this model increased overall tumor burden, measured by liver-to-body weight ratio." (PMID 40394703, 2025). "In a study of 71 HCC tumor samples from Shanghai, China, we found a strong positive correlation between HHLA2 expression and c-Met phosphorylation." (PMID 40394703, 2025). "In vivo studies using mouse models (orthotopic xenografts and hydrodynamic tail vein injection) evaluated HHLA2’s role in tumor growth and metastasis." (PMID 40394703, 2025). "This suggests the potential for HHLA2 expression to be a consequence of inflammatory activity triggered by cellular stimulation induced by a tumor product, specifically CA125 in this instance." (PMID 40255615, 2025).
tumor (continued). "Both in vitro and in vivo studies confirmed that c-Met activation is essential for HHLA2-driven oncogenesis, with c-Met inhibition effectively abolishing HHLA2’s tumor-promoting activities." (PMID 40394703, 2025). "HHLA2 plays dual roles, exhibiting both immunosuppressive and tumor-suppressive functions in endocrine-related tumors, with its expression possibly influenced by the tumor microenvironment." (PMID 40255615, 2025). "Serum HHLA2 levels correlate with tumor expression, potentially facilitating liquid biopsy for patient stratification." (PMID 40394703, 2025). "In contrast, low-risk tumors exhibited higher expression of HHLA2, NRP1 and TNFSF15, which are associated with a more balanced immune response and anti-tumor activity." (PMID 40243888, 2025). "Inhibition of c-Met with PHA665752 effectively reversed HHLA2-mediated tumor-promoting effects in vitro and in vivo." (PMID 40394703, 2025). "This direct activation of c-Met by HHLA2 represents a novel mechanism by which HHLA2 promotes tumor growth and aggressiveness." (PMID 40394703, 2025). "The patients with low HHLA2 expression presented more prominent distant metastasis, advanced tumor node metastasis (TNM) stages, and stages of the depth of tumor invasion." (PMID 38786018, 2024). "In our study, the tumor-infiltrating immune cell model showed that the level of HHLA2 was positively correlated with TAMs in PC, suggesting that HHLA2 was associated with TAMs." (PMID 38762741, 2024). "Our study, through sequencing and immunohistochemical analysis, showed that NSCLC with COPD exhibited down-regulation of HHLA2 expression in the tumor immune microenvironment, particularly in tumor cells." (PMID 38553708, 2024). "They found that TAMs were significantly higher in the HHLA2 low-expression group, which indicates the crucial role of HHLA2 in tumor microenvironment (TME) organization and the process of monocytes developing into TAMs." (PMID 38786018, 2024). "And then, the down-regulated HHLA2 was selected for further investigation due to its relevance to tumor immunity." (PMID 38553708, 2024). "In conclusion, the interactions between HHLA2 and immune cells in the tumor microenvironment are a multidimensional issue, which hopefully will be addressed in future reports in more detail." (PMID 38786018, 2024). "The tumor environment seems to play a crucial role in maintaining HHLA2 expression in ccRCC cells in vivo." (PMID 38786018, 2024). "Statistical analysis showed that HHLA2 expression in tumor tissues was significantly higher than that in adjacent normal tissues." (PMID 38762741, 2024). "High HHLA2 expression was correlated with tumor progression, tumor invasion, more advanced Nevin stage, AJCC stage, and regional lymph node metastasis." (PMID 38786018, 2024). "Overall, 30 out of 63 tumor tissues (47.6%) exhibited high expression of HHLA2 (H-score > 9), and the upregulation of HHLA2 in cancerous tissue was confirmed in another study conducted on 159 cancerous and noncancerous specimens." (PMID 38786018, 2024). "The authors detected HHLA2-positive staining in 77.8% of tumor specimens, while only 22.2% of healthy regions expressed HHLA2." (PMID 38786018, 2024). "The study showed that HHLA2 protein and mRNA levels were elevated in primary tumor tissues, which resulted in metastasis in comparison with primary tumors without metastases (p < 0.001)." (PMID 38786018, 2024). "In MTC, it was shown that the tumor-free survival rate was lower in the patients with high HHLA2 expression compared with the patients with low HHLA2 expression." (PMID 38786018, 2024). "When HHLA2 was down-regulated, this inhibitory effect was weakened, thus promoting the anti-tumor immune system." (PMID 38553708, 2024). "Understanding this mechanism requires more data, and future studies should focus on the differentiation between how HHLA2 expression in tumor cells and HHLA2 expression in other cells of the tumor microenvironment can influence the course of the disease." (PMID 38786018, 2024).
tumor (continued). "KIR3DL3 is expressed in CD8 and NK cells, and its relationship with HHLA2 inhibits T cells and mediates tumor resistance against NK cells." (PMID 38731979, 2024). "There was a positive correlation between HHLA2 expression in the tumor compartment and the age of the patients in a study conducted on 119 EOC cases, but other studies failed to confirm this association." (PMID 38786018, 2024). "Previous research demonstrated that HHLA2 exhibited primary expression on both tumor cell and antigen-presenting cell (APC) membranes, inhibiting human CD4+ and CD8+T cell proliferation and activation when T cell receptor signaling was present." (PMID 38553708, 2024). "Uncovering the diverse functions of HHLA2 expression in different tumor microenvironment cells would be another exciting target for future studies." (PMID 38786018, 2024). "In this study, we established a correlation between high expression levels of CCR4, CCL17, CD73, and HHLA2 in tumor tissues and the poor prognosis in HCC patients." (PMID 38914802, 2024). "In epithelial ovarian cancer, HHLA2 was reported positively correlated with tumor differentiation, the infiltration level of CD8+ T cells, and prognosis." (PMID 38225273, 2024). "HHLA2 is significantly related to EGFR mutations and tumor-infiltrating lymphocyte density in LUAD patients." (PMID 36308553, 2023). "Cytokines, particularly IL10, that induce HHLA2 expression in monocytes fail to upregulate HHLA2 expression in tumor cell lines in vitro." (PMID 37891555, 2023). "Tumor-infiltrating lymphocytes score correlated positively with IHC HHLA2 expression level percentage." (PMID 36982953, 2023). "We conducted principal component analysis demonstrating evidence of the dualistic effect of HHLA2 on tumor development." (PMID 36982953, 2023). "Further, expression of HHLA2 was detected by the immunohistochemistry method in 77 randomly selected tumor slides." (PMID 36982953, 2023). "According to our GSEA results, there was a relation between HHLA2 and the Wnt/βcatenin pathway, which suggests the impact of HHLA2 in tumor development." (PMID 36982953, 2023). "HHLA2 expression in A498 and 786-O ccRCC cell lines was examined in vitro and in subcutaneous tumor xenografts in NSG mice." (PMID 37891555, 2023). "HHLA2 supports tumor development by acting as an inhibitory immune checkpoint through binding with KIR3DL3 in NK and T cells." (PMID 36982953, 2023). "While HHLA2 is expressed in primary tumor cells and ccRCC xenografts, HHLA2 expression is lost during in vitro culture." (PMID 37891555, 2023). "A better understanding of the regulation of HHLA2 in tumor cells and within the tumor microenvironment will facilitate translation of these therapeutic agents into the clinic." (PMID 37891555, 2023). "High concentrations of cytokines, particularly IL-10, can induce HHLA2 expression in monocytes but fail to upregulate HHLA2 expression in clear cell kidney cancer cells; however, the tumor microenvironment in NSG mice can induce HHLA2 expression." (PMID 37891555, 2023). "HHLA2 has been shown to be expressed in ccRCC and other tumor types by immunohistochemistry and mRNA expression." (PMID 37891555, 2023). "CD28H is the co-stimulatory receptor in HHLA2 signaling that can be a target for agonistic antibodies for inducing the effector side of anti-tumor immunity." (PMID 38144305, 2023). "We found that IL-10, which plays an important role in the tumor microenvironment, upregulates HHLA2 in these myeloid immune cells." (PMID 37891555, 2023). "A better understanding of HHLA2 regulation in tumor cells and the tumor microenvironment is crucial for the successful translation of these therapeutic agents into clinical applications." (PMID 37891555, 2023). "ccRCC tissues from patient nephrectomy specimens were dispersed into single-cell suspensions and analyzed for HHLA2 expression after CA9 positive selection for tumor cell purification." (PMID 37891555, 2023).
tumor (continued). "The detailed mechanism elucidating the effect of HHLA2 expression in the TME on tumor progression is yet to be established." (PMID 36598731, 2023). "HHLA2 expression was examined by immunohistochemistry and was detected on approximately 64% and 8% of A498 and 786-O tumor cells, respectively." (PMID 37891555, 2023). "Some studies have reported an interaction between tumor cells, T cells, and stromal cells to regulate HHLA2 expression." (PMID 36598731, 2023). "We also evaluated the possible interaction between HHLA2 expression in tumor cells and stromal cells, and CAFs in TME." (PMID 36598731, 2023). "We found that patients with higher levels of HHLA2 had greater load of circulating tumor cells, a crucial metastasis indicator (P=0.039) by chi-squared tests." (PMID 35371079, 2022). "More experimental validations are required to confirm HHLA2’s biological roles and its relation with tumor immune microenvironment." (PMID 35371079, 2022). "Overall, our study provided a novel perspective into the role of HHLA2 and its interaction with tumor immune microenvironment (TIME) in HCC." (PMID 35371079, 2022). "Some B7 family immune checkpoints, particularly PD-L1, PD-L2, B7-H3, B7-H4, VISTA and HHLA2, have been identified as playing a significant role in the control of tumor immune responses." (PMID 36499340, 2022). "It was recently reported that HHLA2 promotes tumor progression by affecting the functions of immune cells in tumor microenvironment." (PMID 35371079, 2022). "In particular, HHLA2 protein expression in samples of Stage 1 was higher than in stage 4, but normal tissue had a lower protein expression than any tumor stage (Figure A9c)." (PMID 35565241, 2022). "The cellular models based on ccRCC cell lines such as 786-O and ACHN, were established by operating METTL3 and HHLA2 via knockdown or overexpression, followed by in vitro cellular function studies and in vivo subcutaneous transplantation tumor model." (PMID 35794583, 2022). "Analytic data of immune microenvironment showed that the expression level of HHLA2 was positively correlated to the density of CD8+ T cells in the tumor microenvironment." (PMID 36003385, 2022). "Current research on HHLA2 has mainly focused on its regulation of the tumour microenvironment, particularly in the recruitment of TILs." (PMID 33962626, 2021). "We found a high positive rate of PD-L1 and HHLA2 proteins in the tumor subarea, whereas other markers had predominantly stromal expression." (PMID 35145510, 2021). "It has been shown that normal epithelial cells expressed the highest level of HHLA2 compared with tumor cells." (PMID 34639059, 2021). "A low level of HHLA2 mRNA expression correlates with disease stage, distant metastasis, and tumor invasion depth in the blood of patients with GC." (PMID 34639059, 2021). "The study results also suggest that HHLA2 is expressed in well-differentiated tumours, suggesting that HHLA2 is an indicator of lower malignant tumour behaviour." (PMID 33962626, 2021). "In this study, we found that in addition to be an inhibitory checkpoint in NSCLC, HHLA2 also contributed to tumor progression via directly inhibiting malignant behaviors and regulating M2 polarization of TAMs." (PMID 34152094, 2021). "χ2 test revealed a significant association between HHLA2 expression and the CD8+ T-cell count in the tumour (p = 0.017)." (PMID 33962626, 2021). "Further analyses showed that tumoral HHLA2 levels and stromal expression of several QIF markers (including PD-L1, B7H3 and Galectin-9) were associated with tumor phenotype, microenvironmental immunity level and clinical outcomes." (PMID 35145510, 2021). "The broad expression pattern of HHLA2 showed that HHLA2 has a role in developing tumors by inhibiting anti-tumor immune responses." (PMID 34639059, 2021). "Patients with elevated tumoral HHLA2 expression or stromal B7H3 expression were more likely to receive EI resection of the tumor lesions." (PMID 35145510, 2021).